ANKRD61 (ankyrin repeat domain 61)
Tractability: No criterion of Open Targets' tractability assessment is met for any kind of drug.
Gene: Protein-coding gene on chromosome 7 (6,031,376 to 6,036,552, forward strand). Ensembl gene ENSG00000157999.
Subcellular location (Human Protein Atlas): Nucleoplasm
Gene Ontology:
Cellular component: nucleoplasm
Genetic constraint (gnomAD): Loss-of-function variants: 8 observed, 9.55 expected, observed/expected ratio (o/e) 0.84, 90% interval 0.49 to 1.5. That is too few expected variants to judge how well the gene tolerates losing a copy. Missense variants: 516 observed, 541.49 expected, observed/expected ratio (o/e) 0.95, 90% interval 0.89 to 1.02. Synonymous variants: 198 observed, 215.97 expected, observed/expected ratio (o/e) 0.92, 90% interval 0.82 to 1.03.
Homologues: Orthologues: chimpanzee ANKRD61 (99% identical), macaque ANKRD61 (87% identical), dog ANKRD61 (79% identical), pig ANKRD61 (75% identical), rat Ankrd61 (74% identical), mouse Ankrd61 (72% identical), guinea pig ANKRD61 (71% identical), rabbit ANKRD61 (65% identical), Drosophila melanogaster wtrw (25% identical), Caenorhabditis elegans trpa-1 (23% identical). Paralogues in human: ANKRD54 (16% identical).